IGF1 (insulin like growth factor 1)
Diseases named in the same sentence as IGF1 in open-access papers (continued):
Sharing a sentence is not in itself a finding about the gene and the disease.
colon carcinoma (continued). "However, pretreatment with HP, SC, and Sumac suppressed IGF-1-stimulated phosphorylation of AKT in all colon cancer cells." (PMID 34361052, 2021). "Indeed, previous studies showed that suppression of IGF-1R decreases ABCC2 expression and promoted drug sensitivity in human colon cancer cells, and that IGF-1 increased the expression of ABCC1, ABCC2, and ABCC3 in both leukemia cells and ovarian cancer cells." (PMID 33291663, 2020). "The exogenous IGF1 promoted CSC phenotypic changes in colon cancer cells." (PMID 30257507, 2018). "This association might be explained by the biological hypothesis that increased levels of circulating free IGF-1 and decreased levels of insulin-like growth factor binding protein-3 (IGFBP-3) can increase colon cancer risk." (PMID 29484135, 2018). "Importantly, we observed a correlation between IGF‐1 pathway activation and the infiltration of macrophages with active p38 in samples from ulcerative colitis and colon cancer patients." (PMID 29907597, 2018). "We established 5-FU-resistant colon cancer cell lines by culturing these cells with exogenous IGF1." (PMID 30257507, 2018). "In addition, IGF-1 is upregulated in colorectal tumor tissues, whereas adiponectin is known to prevent colon tumor growth." (PMID 28170448, 2017). "IGF-1 has also been shown to enhance the growth of MC38 colon cancer allografts in rodent models." (PMID 29259973, 2017). "In a study of 69 patients with KRAS exon 2 mutant CRC, IGF-1 expression was higher in rectal than colon tumors, approaching statistical significance (P = 0.06) and suggesting that rectal cancers harbor oncogenic pathways that are different from colon cancers." (PMID 29156800, 2017). "Thus, we suggest that the activation of ERK1/2 and JNK signaling by insulin and IGF-1, at least in part, is responsible for regulating the development and formation of colon cancer with T2DM." (PMID 26901856, 2016). "The results revealed that insulin/IGF-1 inhibits colon cancer cells apoptosis in vitro." (PMID 26901856, 2016). "Furthermore, control of GH and IGF-1 levels should be paramount to mitigate comorbidities such as colon cancer." (PMID 28025627, 2016). "In addition, PD98059, a MEK inhibitor, was previously shown to block HIF-1α protein synthesis and inhibit HIF-stimulated VEGF expression in human colon cancer cells treated with IGF-1." (PMID 26882567, 2016). "Our results also indicated that colon cancer tumor cells secrete IGF-1." (PMID 27683110, 2016). "Moreover, colon cancer-derived insulin-like growth factor-1 (IGF-1) increased Arg1 expression, and treatment with the IGF1R inhibitor AG1024 inhibited that increase." (PMID 27683110, 2016). "Moreover, there was a significant increase in spheroid formation in IGF-1 stimulated cells compared to vehicle treated controls; suggesting that colon cancer cells respond to IGF-1 stimulation by increasing proportion of CSCs." (PMID 25895029, 2015). "Finally, both in vitro and animal studies demonstrate the ability of IGF-1 to increase colon tumor cell growth." (PMID 24732966, 2014). "Moreover, increased serum level of IGF-1 in colon cancer patients was demonstrated to correlate with more severe disease." (PMID 22159423, 2012). "Resveratrol suppressed IGF-1 stimulated HT-29 colon cancer cell proliferation." (PMID 20504360, 2010). "Furthermore, C/EBP-β regulates energy balance, and promotes growth of colon cancer cells in part via activation of IGF-1, insulin, and leptin." (PMID 21048943, 2010).
colon carcinoma (continued). "However, the relationship between adiponectin and colon cancer was not directionally consistent in sensitivity analyses whilst the association between IGF-1 and colon cancer did not survive multiple testing correction." (PMID 36558416, 2022). "In addition, it is thought that the continuous high levels of GH and IGF1 may facilitate the growth of pre-existing colon tumors." (PMID 33389987, 2021). "Pretreatment with high phenolic sorghum extracts weakened the IGF-1-stimulated phosphorylation of AKT in three human colon cancer cells, indicating that growth factor/receptors/PI3K/AKT pathways could be an efficient target for cancer prevention using high-phenolic sorghum bran." (PMID 34361052, 2021). "In addition, an increased IGF1 mRNA was detected in the methotrexate-resistant colon cancer cells." (PMID 30257507, 2018). "Furthermore, IGF-1 secreted from colon cancer cells also influenced macrophage polarization." (PMID 27683110, 2016). "Next, we examined whether IGF-1 levels in colon cancer CM were regulated by the EGFR pathway." (PMID 27683110, 2016). "The increased insulin and IGF-1 may be responsible for the developing of colon cancer." (PMID 26901856, 2016). "Moreover, IGF-1 induced cellular migration and invasion in colon carcinoma cells." (PMID 26360832, 2015). "Additionally, exogenous IGF1 increases the growth and metastasis of colon cancer in mice." (PMID 25699021, 2015). "It has been shown that simultaneous inhibition of the insulin receptors, IGF1 and MET receptors as well as the epidermal growth factor receptors (EGFR) enhances efficacy of EGFR-inhibitors in colon cancer xenografts." (PMID 40677714, 2025). "This study reports that CAFs isolated from colon cancer tissue, TGF-β1-induced CAFs, or HCT116 co-cultured CAFs secrete more cytokines and growth factors represented by IGF1, ELN, and SFRP2." (PMID 40659611, 2025). "In colon cancer cells transduced with a Klotho lentiviral construct, the investigators showed that Klotho downregulates the expression of IGF-1, PI3K, and AKT (mRNA and protein), with subsequent inhibition of growth and invasion of colon cancer cells." (PMID 32585905, 2020). "New evidence has demonstrated that the overexpressions of IGF-1 and IGF-1R contribute to the development and progression of colon cancer in patients and in an AOM-DSS-induced colorectal carcinogenesis model." (PMID 31480481, 2019). "IGF1 contributes to the cell cycle progression and inhibits the apoptosis pathway; IGF1 also promotes cell growth in CRC by activating the VEGF gene and, therefore, supports cancer progression of human colon cancer cells." (PMID 31336886, 2019). "Focusing on IGF/IGF-1R signaling, in vitro treatment with EGCG reduced IGF-1 and the activated form of IGF-1R levels and increased IGFBP-3 in human hepatoma and colon cancer cells, indicating that EGCG exhibited inhibitory actions on the IGF/IGF-1R axis." (PMID 30205425, 2018). "Of note, colon tumors from IGF‐1‐ΔMC mice exhibited reduced macrophage infiltration compared to those from WT mice, further suggesting the implication of IGF‐1 in immune cell recruitment." (PMID 29907597, 2018). "Accelerative colon tumor growth was found in a mouse model of T2DM with db/db mice which got high level of endogenous insulin and IGF-1." (PMID 26901856, 2016). "Accelerative colon tumor growth was found in a mouse model of T2DM which got high level of insulin and IGF-1." (PMID 26901856, 2016).
colon carcinoma (continued). "It has been shown that IGF-1 increases Hif1α synthesis through PI3K and MAPK pathways in colon cancer cells." (PMID 27148974, 2016). "Consistent with the finding in colon cancer cells (HCT116), treatment with rapamycin (100 ng/ml) for 2 h inhibited the basal or IGF-1-stimulated adhesion of Rh1 and Rh30 cells." (PMID 25762619, 2015). "Here we show that the MC38 cell line, derived from a murine colon cancer, expresses IRs and IGF-1Rs and is insulin sensitive, as treatment with HI, X10 and IGF-1 results in activation of the PI3K and MAPK signalling pathways and increases proliferation." (PMID 24260289, 2013). "High IGF-1 levels have been found in several sarcoma subtypes and IGF-1R overexpression in breast, lung, prostate, or colon cancer has been shown to accelerate cancer progression and enable anchorage-independent growth." (PMID 24212944, 2011). "We have previously shown that RSV suppressed IGF-1 signaling via suppression of IGF-1R resulting in G1 cell cycle arrest and suppression of proliferation in HT-29 and SW480 colon cancer cells." (PMID 21849056, 2011). "Multivariable adjusted ORs and 95% confidence intervals of colorectal and colon cancer by median levels of IGF-1, C-peptide, IGF-1/IGFBP3 ratio and vitamin D, HPFS and NHS combined." (PMID 22216097, 2011). "PRL-3 expression was reported to be regulated at transcriptional level by mitogenic cytokines, such as IL-6, IL-21, HGF or IGF-1 in myeloma cell lines, or as TGF-β in colon cancer cell lines." (PMID 21466710, 2011). "Human colon cancer cells were grown in DMEM with 2.5% charcoal-stripped serum for 24 h and treated with DMSO (solvent control), IGF-1 (10 nM), and different concentrations of resveratrol (50, 100 and 150 μM)." (PMID 20504360, 2010). "Additionally, immunofluorescence staining demonstrated that in colon cancer, both ELN and IGF1 were primarily expressed in CAFs, with some of IGF1 also detected in cancer cells." (PMID 40659611, 2025). "In this regard, IGF1 has been shown to induce HIF-1α protein synthesis at the translational level, without affecting HIF-1 gene transcription or protein stability in colon cancer cells and an increase in HIF-1α mRNA levels has been demonstrated after stimulation with IGF1 in several cells models." (PMID 29212519, 2017). "With regard to the IGF/IGF-1R axis, treatment with EGCG showed decreased levels of IGF-1 and reduced IGF-1R activation, whereas the levels of IGFBP-3 were found to be increased in colon cancer cells." (PMID 28445390, 2017). "We speculated that insulin or IGF-1 got the same effects on MC38 cells, a mouse derived colon cancer cell line." (PMID 26901856, 2016). "A previous report on colon cancer showed that attenuated IGF-1R protein levels could suppress cell proliferation and elevate apoptosis even in the presence of IGF-1 via suppression of IGF-1R/Akt/Wnt signaling pathways and activation of p5332." (PMID 27646050, 2016). "As shown in Zaafar’s report, the level of IGF-1 and VEGF were all increased in diabetic mice and diabetic mice had higher susceptibility to DMH-induced colon cancer compared to nondiabetics." (PMID 25329503, 2014). "IGF1 has been reported to amplify Fas antibody-induced apoptosis in human osteoblasts, to stimulate TNFα-induced apoptosis in murine myoblasts and preadipocytes, and to enhance Apo2L/TRAIL-induced apoptosis in human colon carcinoma cells." (PMID 23091403, 2012). "Several but not all prospective studies have found high IGF-1 or IGF/IGFBP-3 ratio and high C-peptide to be associated with an increased risk of colorectal or colon cancer." (PMID 22216097, 2011). "RSV (150 μM) suppressed the talin and phosphorylated Fak protein levels even in the presence of IGF-1, a potent mitogen, indicating that RSV anti-cancer effects against human colon cancer cell might be partly due to disruption of cell-ECM interaction." (PMID 21849056, 2011).
colon carcinoma (continued). "Insulin-like growth factor-1 also stimulates the proliferation and survival of MM cells and has been described to increase the expression of VEGF and thus angiogenesis in colon cancer cells." (PMID 14997210, 2004). "Furthermore, recent observational studies reported that IGF1 levels have been shown to be elevated in non-acromegalic populations with colon cancer." (PMID 34858769, 2021). "Tumor tissue extracted from 48 colon cancer patients significantly overexpressed IGF-1R and IGF-2 mRNA, but not IGF-1 mRNA." (PMID 22159423, 2012). "In order to establish the efficacy of resveratrol against IGF-1 induced colon cancer growth, we utilized HT-29 and SW480 (IGF-1R constitutively active) human colon cancer cell lines and treated them with/without IGF-1 and/or resveratrol." (PMID 20504360, 2010).
depression (141 papers, 2006 to 2026). "In the complete-case sample, the only significant correlation was a positive association between increased IGF-1 levels and depression scores measured by the BDI-II in the MBSR+CCT group (rp = 0.56, padj = 0.021)." (PMID 40283415, 2025). "There was a positive association between blood IGF-1 and the presence of a depression diagnosis, with a moderate effect size (β = 0.26; p = 0.036; d = 0.66)." (PMID 40284205, 2025). "Our data indicate that decreased IGF-1 levels are associated with increased symptom severity and heightened rates of depression and anxiety, highlighting IGF-1 as a potential biomarker for post-TBI recovery." (PMID 40697802, 2025). "Findings suggest that decreased IGF-1 is associated with increased post-injury symptom severity, depression, and anxiety." (PMID 40697802, 2025). "The association between IGF-1 and depression in the acute and recovered AN phases is consistent with recent meta-analytical evidence which showed increased circulatory IGF-1 in patients with depressive disorder compared to HCs." (PMID 40284205, 2025). "The study was made in the region of Pomerania, and found that IGF-1 baseline levels below 10% increased the 5-year risk of depression in women." (PMID 40141202, 2025). "In men, high levels of circulating IGF-1 have been linked to depression; in women, IGF-1 is inversely linked to depressive disorders." (PMID 39286983, 2024). "Aside from glutamate, IGF-1 is also widely distributed in the CNS and is known to underlie the pathogenesis of depression." (PMID 38674428, 2024). "Inflammation and trophic factors (brain-derived neurotrophic factor [BDNF], vascular endothelial growth factor, glial cell line-derived neurotrophic factor, and insulin-like growth factor-1) are associated with depression in the general population." (PMID 33104946, 2021). "The study concluded that elevated IGF-1 levels were significantly associated with depression and impaired treatment response." (PMID 34362162, 2021). "Then, we analyzed associations of IGF-1 variants with neuropsychiatric symptoms after mTBI, including anxiety, depression, dizziness, and sleep disturbances." (PMID 31787098, 2019). "When compared with data from the Study of Health in Pomerania in Germany, our results were in agreement with the finding that having a low IGF-1 level was associated with higher risk of developing depression symptoms among women." (PMID 27648920, 2016). "Our results are also in agreement with the second existent study, which used data from The Longitudinal Aging Study Amsterdam, where associations were found between median levels of IGF-1 and lower risk of both prevalent and incident depression symptoms." (PMID 27648920, 2016). "In conclusion, in the present study of older adults, there was some evidence that moderate levels of IGF-1 levels conferred a reduced risk of depression." (PMID 27648920, 2016). "Although suggestions for mechanisms of action have been posited, it remains possible that IGF-1 levels are a proxy for other factors that are causally related to depression (residual confounding)." (PMID 27648920, 2016). "In conclusion, taken together, in the present study of older adults, having IGF-1 values at opposite ends of the continuum was associated with a somewhat increased risk of depression symptoms and physician-diagnosis of depression." (PMID 27648920, 2016). "A ‘U'-shaped pattern of risk was again observed for the IGF-1–depression association in both genders based on symptomatology." (PMID 27648920, 2016). "The main finding of this study of older people was that having IGF-1 levels at opposing ends of the continuum was associated with a slightly higher risk of depression symptoms." (PMID 27648920, 2016).